IL18 (interleukin 18)
Diseases named in the same sentence as IL18 in open-access papers (continued):
Sharing a sentence is not in itself a finding about the gene and the disease.
sarcopenia (12 papers, 2021 to 2026). Progressive decline in muscle mass due to aging which results in decreased functional capacity of muscles. "Higher plasma IL-18 concentrations were also associated with sarcopenia in a population of older people." (PMID 41592067, 2026). "Notably, hexanoic acid (C6) showed the strongest associations with pro-inflammatory markers, particularly IL-18 and NT-proBNP, highlighting its potential relevance in sarcopenia-related inflammation." (PMID 41516422, 2026). "From the proteomic analysis, we hypothesised that elevated IL-18BP would reduce the pro-inflammatory effects of IL-18 and that this would lead to positive association of IL-18BP with muscle mass or strength in individuals with sarcopenia." (PMID 41592067, 2026). "Univariate logistic regression showed that higher CXCR2 and CXCR1 expression increased sarcopenia risk, while lower LPL and IL18 expression was protective." (PMID 40625358, 2025). "The study found that, compared with those in non-sarcopenia patients, the serum levels of IL-6, IL-18, TNF-α, TNF-like weak inducing factor of apoptosis (TWEAK), and leptin were significantly increased in sarcopenia patients." (PMID 37584041, 2023). "HMGB1 is upregulated in muscle inflammation, and circulating levels of the proinflammatory cytokine interleukin-18 (IL-18) are upregulated in patients with sarcopenia, a muscle-wasting disease." (PMID 36497194, 2022). "The SOMAscan study identified other proteins that associated with loss of strength that are not components of the IL-18 signalling system, but which have not been followed up either in the acute sarcopenia cohort or the LACE cohort." (PMID 41592067, 2026). "In the acute sarcopenia cohort, while plasma IL-18 did not change in response to surgery, plasma IL-37 was significantly increased in post-surgery plasma samples compared to the pre-surgery samples." (PMID 41592067, 2026). "Six cytokines and growth factors were identified to relate to the sarcopenia traits and telomere length: CTACK (cutaneous T‐cell attracting chemokine), eotaxin, IL16 (interleukin‐16), IL18 (interleukin‐18), MIP1b (macrophage inflammatory protein 1b) and PDGFbb (platelet‐derived growth factor BB)." (PMID 38556722, 2024). "NLRP3 and Myd-88 are key orchestrators of chemotherapy-related cardiovascular diseases (CTRCD) and sarcopenia; cytotoxic properties are principally mediated by high levels of pro-inflammatory cytokines and chemokines, such as IL-1β, IL-6, IL-8, CXCL-2, TGF-β, IL-18 and others." (PMID 38672567, 2024).
acute tubular necrosis (11 papers, 2012 to 2024). "Increased IL18 levels are associated with acute tubular necrosis, urinary tract infections, and prerenal failure and therefore may not purely reflect an injury to the kidney." (PMID 32411464, 2020). "Urinary levels of IL-18 have high sensitivity and specificity in identifying acute tubular necrosis, and an early increase in IL-18 levels correlates with the severity of AKI." (PMID 39201939, 2024). "Studies have shown that IL-18 levels are significantly higher in the urine of patients with acute tubular necrosis and DGF." (PMID 38611630, 2024). "Urinary IL-18 has been reported to be increased in patients with acute tubular necrosis after kidney transplantation." (PMID 33732720, 2021). "Although IL-18 mediates ischemic acute tubular necrosis, its levels in urine concentration have only moderate diagnostic value for the early detection of AKI." (PMID 27847811, 2016).
cervical carcinoma (11 papers, 2013 to 2024). A carcinoma arising from either the exocervical squamous epithelium or the endocervical glandular epithelium. "In uterine cervix cancer, there are some IL-18 polymorphisms that have been linked to cancer progression and it has been found that a reduction of plasma IL-18 increases the risk of developing cervical cancer." (PMID 31554368, 2019). "This reduced IL-18 mRNA expression can increase the risk of developing cervical cancer." (PMID 31554368, 2019). "The objective of this study was to analyze the gene expression profile of the proinflammatory interleukins, (IL-1β and IL-18) in patients with premalignant lesions and cervical cancer." (PMID 31554368, 2019). "Infection by high-risk HPV causes cervical cancer via its oncoprotein, HPV16 E6/E7, inhibits interleukin 18-induced interferon-γ production in NK cells, which may promote viral pathogenesis." (PMID 33995627, 2021). "Moreover, while still transcribed in immortalized keratinocytes, the same transcriptional down-regulation was also detected in cervical carcinoma cells when other cytokines such as IL-1α, IL-18 and IL-33 were monitored by q-PCR." (PMID 23935506, 2013). "Here we show that the expression of IL6 and IL18 is modulated by TLR4 and SARM1 in cervical cancer cells." (PMID 35468924, 2022). "Besides, the interaction between cervical cancer cell-derived TSLP and eosinophils regulates IL-18 and VEGF production, resulting in stimulation of the angiogenesis of human umbilical vein epithelial cells." (PMID 33652749, 2021).
fungal infections (11 papers, 2017 to 2025). "Similar effects of IL-18 have been reported in fungal infections caused by Aspergillus, Cryptococcus neoformans, Candida and Paracoccidioides brasiliensis." (PMID 40489556, 2025). "The signalling axis of β-glucan, DECTIN-1, SYK and CARD9 is a central pillar of inflammasome activation, as well as the release of inflammasome/pyroptosis-associated IL-1β and IL-18 in fungal infection and beyond." (PMID 38515333, 2024). "Additionally, the association of the IL18-607 A-allele with the more severe forms of PCM described herein collaborates with previous reports on different genes emphasizing the influence of genetic background on the outcome of this mycosis." (PMID 33117339, 2020). "Previous reports showed IL-18 enhanced protective Th1 immunity against fungal infections such as Aspergillus and C. albicans." (PMID 40489556, 2025). "As a member of alarmins, IL-18 plays important roles in host protection against bacterial, viral, and fungal infections." (PMID 40489556, 2025). "In agreement, the induction of IL-18 has been observed during systemic and mucosal fungal infections." (PMID 33643264, 2021). "Interleukin-18 is a crucial cytokine that mediates innate and adaptive immunity and likely plays a key role during fungal infection." (PMID 33643264, 2021). "WT BMDMs released a significant amount of IL-18 after fungal infection, whereas the Casp1/11–/–Ripk3–/–Casp8–/– BMDMs released significantly less." (PMID 33109609, 2020). "Given the clear role for ZBP1 in C. albicans- or A. fumigatus-mediated inflammasome activation and PANoptosis, we assessed the release of the inflammatory cytokine IL-18 after fungal infection." (PMID 33109609, 2020). "Both IL-1β and IL-18 have been shown to exert protective effects against various fungal infections." (PMID 34769275, 2021). "Understanding the role of IL-18 in the immune response to fungal infections may have implications for developing novel therapeutic approaches, such as targeting IL-18 signaling pathways to modulate the immune response and improve outcomes in patients with fungal infections." (PMID 40315193, 2025). "Additionally, we found increased IL-2 expression in lesional skin and in PBMCs exposed to S. globosa in vitro, and blocking IL-2 with its antibody further decreased Th2 induction, indicating that IL-2 indeed participates in driving Th2 response with IL-18 in this fungal infection." (PMID 40489556, 2025). "Moreover, western blot analysis revealed dramatically decreased levels of pyroptosis-associated proteins ASC, cleaved CASP1, GSDMD, cleaved GSDMD, cleaved IL-1β and cleaved IL-18 in the Ad-NLRP3-shRNA group compared with the Ad-GFP-shRNA group during fungal infection." (PMID 35463001, 2022). "During fungal infection, the NLRP3 inflammasome formation in immune cells leads to the activation of CASP1, which then cleaves the proinflammatory cytokines IL-1β and IL-18 to their bioactive forms and induces pyroptosis." (PMID 35463001, 2022). "During fungal infection, the activation of the NLRP3-ASC-CASP1 inflammasome leads to cleavage of pro-CASP1, which then processes the proinflammatory cytokines IL-1β and IL-18 to their bioactive forms and cleaves GSDMD to trigger pyroptosis." (PMID 35463001, 2022).
Granuloma (11 papers, 2010 to 2025). A compact, organized collection of mature mononuclear phagocytes, which may be but is not necessarily accompanied by accessory features such as necrosis. "Furthermore, P. acnes-primed IL-18-deficient mice exhibited granulomas in the liver comparable with P. acnes-primed WT mice, but were resistant to acute hepatitis induced by LPS." (PMID 30717382, 2019). "In the present study, B cells cocultured with Mtb-infected monocytes significantly increased IL-1Ra, IL-18, and IL-10 production, suggesting a possible role of IL-10–producing Bregs in regulating excess inflammation in granulomas." (PMID 41208111, 2025). "This cascade culminates in the expression of many NF-κB-inducible genes, including CCL2, IL1B, IL12, IL18 and TNF, causing natural killer (NK) and T cells to release IFN-γ and TNF-α, which ultimately results in granuloma formation." (PMID 22182502, 2011). "Since they fail to develop hepatic granulomas, P. acnes-primed Myd88−/− mice lack the production of robust IL-18 after P. acnes priming, presumably resulting in escape from the liver injury." (PMID 20634907, 2010). "Upon LPS challenge P. acnes-primed Il18−/− mice having normally dense hepatic granulomas develop the endotoxin shock syndrome comparably as P. acnes-primed WT mice." (PMID 20634907, 2010). "Unlike MyD88-deficient mice, P. acnes-primed TRIF-deficient mice normally develop hepatic dense granulomas, but do not release IL-18 or develop liver injury." (PMID 30717382, 2019). "TNF, IL-1β, IL-18, IL-1RA, IL-8, MCP-1, and MIG were all present at significantly (p<0.05–0.0001) lower levels in secondary granulomas, with a trend towards lower IFN-γ." (PMID 30312351, 2018). "In granulomas, levels of IL-1β, IL-1RA, and IL-18 were not affected by IL-1Rn treatment in the subset examined." (PMID 32477361, 2020). "Conversely, P. acnes-primed Trif−/− mice, Caspase1−/− mice, Asc−/− mice and Nlrp3−/− mice all have normal dense granulomas in their livers, but fail to develop liver injury after LPS challenge, concomitant with the absence of the serum IL-18 increase." (PMID 20634907, 2010). "Considering the importance of IFN-γ-producer cells in typical TB granuloma formation, we therefore hypothesize that individuals with a defective NLRC4/IL18 axis are not able to effectively contain mycobacteria within granulomas, leading to eventual extra-pulmonary dissemination." (PMID 33193317, 2020).
idiopathic pulmonary fibrosis (11 papers, 2011 to 2025). Idiopathic pulmonary fibrosis (IPF) is a nonneoplastic pulmonary disease that is characterized by the formation of scar tissue within the lungs in the absence of any known cause. "have reported IL-18 and IL-18R are involved in the pathogenesis of idiopathic pulmonary fibrosis/usual interstitial pneumonia." (PMID 39847405, 2025). "IL-18 is also involved in the development of inflammatory lung diseases including pulmonary inflammation, asthma, lung injury and idiopathic pulmonary fibrosis (IPF)." (PMID 21915293, 2011). "IL-18 and IL-1β levels in bronchoalveolar lavage fluid (BALF) were also elevated in RA-usual interstitial pneumonia (RA-UIP) patients." (PMID 35095918, 2021).
inflammatory skin disease (11 papers, 2015 to 2024). Inflammatory skin disorders covers a broad category that includes many conditions ranging in severity, from mild itching to grave medical health complications These disorders are common in people of all ages and races. "Therefore, regulating the NLRP3 inflammasome and its associated cytokines, including IL-1β, IL-18, and IL-6, is important in preventing inflammatory skin diseases." (PMID 37175425, 2023). "Further research is needed to explore the therapeutic potential of targeting IL-18 and IL-37 in inflammatory skin diseases, with ongoing and future studies likely to provide deeper insights and new treatment avenues." (PMID 39126010, 2024). "Several studies have shown that prolonged exposure to O3 can increase oxidative damage and promote release of pro-inflammatory cytokines, such as interleukin-1β (IL-1β) and IL-18, leading to various inflammatory skin diseases." (PMID 38393203, 2024). "Comparing the different inflammatory skin diseases showed significantly increased concentrations of IL-18, especially in patients diagnosed with urticaria." (PMID 38539560, 2024). "Additional studies regarding the effect of UVB-induced IL-22 production and IL-22Rα expression on the production of IL-1α, IL-6, and IL-18 will provide a basis for further understanding the role of IL-22 in the control of inflammatory skin disease." (PMID 28558005, 2017). "Assessment of Ccl7, Il18, and Il1b expression is most indicative of distinguishing skin rejection from skin inflammatory disorders." (PMID 25756043, 2015). "To date, many reports revealed the dysregulation of IL-18 in inflammatory skin diseases, and IL-18 has been speculated to be a possible marker for diverse disorders." (PMID 36742296, 2023). "IL-18, a member of the IL-1 family, is involved in autoimmune and skin inflammatory disorders." (PMID 36012289, 2022). "Given that IL-1α and IL-6 are involved in the pathogenesis of skin diseases caused by proliferation of keratinocytes, IL-22-dependent regulation of UVB-induced IL-1α, IL-6, and IL-18 production may be important in the mechanism of inflammatory skin diseases." (PMID 28558005, 2017).
Myocardial fibrosis (11 papers, 2014 to 2026). "Accumulation of IL‐18 in the body could cause cardiomyocyte hypertrophy and myocardial fibrosis, and myocardial dysfunction was improved after using IL‐18 neutralizing antibodies." (PMID 38617433, 2024). "In rats, cardiac function, serum levels of cardiac enzymes, apoptosis, myocardial fibrosis, and levels of IL-1β, IL-18, TNF-α, TLR2, and pyroptosis-related molecules were detected." (PMID 39018487, 2024). "Many studies have shown that IL-18 and certain genetic factors play a role in the development of myocardial fibrosis and sickle cell cardiomyopathy." (PMID 34277213, 2021). "IL-18 also induces fibroblast expression of fibronectin, a prominent extracellular matrix protein, a mechanism possibly involved in myocardial fibrosis." (PMID 25152568, 2014). "Concurrently, EMPA treatment effectively suppressed activation of the NF-κB/NLRP3 signaling pathway, accompanied by reduced levels of IL-1β and IL-18, suggesting decreased levels of cardiomyocyte pyroptosis and markedly alleviated inflammatory infiltration and myocardial fibrosis." (PMID 42099788, 2026). "Blockade of either NLRP3 or IL-18 additionally reduced production of chemokines that attract monocytes, lowered expression of IL-6, with blunted proinflammatory macrophage infiltration and ameliorated myocardial fibrosis." (PMID 38093747, 2023). "Likewise, in situations of pressure overload–mediated cardiac damage, ROS and NF-κB stimulated NLRP3 inflammasome activation leading to increased IL-1 and IL-18 production and increased inflammatory monocyte infiltration and myocardial fibrosis." (PMID 38093747, 2023). "It was shown that pinocembrin can inhibit pyroptosis by activation of Nrf2/Sirt3 signaling pathway, LVEF, LVFS, LVIDd, LVID, and myocardial fibrosis were improved, and the expressions of LDH, CK-MB, IL-1β, and IL-18 were reduced." (PMID 35509275, 2022). "In summary, BYHWD exerts anti-inflammatory effects by down-regulating the expression of inflammatory factors such as IL-6, IL-1β, IL-18, and NLRP3, and inhibiting the JAK/STAT and TLR4/NF-κB signaling pathways, thereby slowing down the process of myocardial fibrosis." (PMID 40881586, 2025).
nephritis (11 papers, 2015 to 2026). Inflammation of renal tissue. "Administration of exogenous IL-18 to these mice aggravated disease activity and nephritis, and IL-18-deficient mice or mice treated with anti-IL-18 in the MRL/lpr model showed improved survival rates and reduction of proteinuria." (PMID 38031150, 2023). "IL-18 has long been implicated in promoting nephritis development in SLE in the capacity of a prominent Th-1 response driver." (PMID 33919154, 2021). "Taken together, our findings provide evidence to support an additional pathogenic role of IL-18 in that it may promote nephritis through the mediation of neutrophil dysfunction via the upregulated expression of IL18RAP." (PMID 33919154, 2021). "Meta-analysis demonstrates significantly elevated serum IL-18 levels in LN patients with active nephritis compared with renal-sparing SLE, highlighting its role as a key mediator of renal damage." (PMID 41142814, 2025). "We recently showed, in the largest study to date, that serum IL-18 was elevated in SLE compared to healthy subjects, and was significantly associated with the presence of nephritis." (PMID 33889157, 2021). "Additional evidence for the critical role of IL-18 is provided by multivariate analysis, which identified lower IL-18BP and higher sIL-1R4 as distinguishing features of patients with active nephritis." (PMID 29422069, 2018). "Intraperitoneal administration of recombinant IL-18 has been demonstrated to exacerbate renal disease and in vivo inhibition of IL-18 by anti-IL-18 cDNA vaccination attenuates lymphoproliferation and nephritis and increases lifespan." (PMID 29422069, 2018). "MRL/lpr mice have increased levels of serum IL-18 compared to control animals and the administration of exogenous IL-18 to these mice worsened disease activity and nephritis." (PMID 29930551, 2018). "Surprisingly, the fast worsening general health status, quantified as ‘survival’, is unaffected by deletion of IL-18 expression, although specific parameters of nephritis are ameliorated." (PMID 26465326, 2015). "PLS identified sIL-1R4, sIL-1R2 and anti-dsDNA as variables distinguishing patients with active from those with inactive disease; sIL-1R4, IL-18BP and anti-dsDNA identified patients with active nephritis; sIL-1R4, C3, IL-18 and free IL-18 identified patients with haematological involvement." (PMID 29422069, 2018). "As IL-18 has been implicated in nephritis development, we specifically compared SLE patients with biopsy-confirmed nephritis (LN group, n = 55) with patients without any renal manifestations for at least 10 years (non-LN, NLN group, n = 40)." (PMID 33919154, 2021).
non-alcoholic fatty liver disease (11 papers, 2016 to 2025). "For example, because IL-18 has recently been shown to have an unfavorable predictive role in some inflammatory contexts (non-alcoholic fatty liver disease (NAFLD)), for certain therapeutic settings it might be best to utilize 27 or 27pepL single therapies." (PMID 34209203, 2021). "Additionally, verapamil can treat non‐alcoholic fatty liver disease by inhibiting the TXNIP/NLRP3 pathway and reducing the level of IL‐1β and IL‐18 to attenuate hepatic metaflammation." (PMID 34031983, 2021).